ST14 (ST14 transmembrane serine protease matriptase)
Diseases named in the same sentence as ST14 in open-access papers (continued):
Sharing a sentence is not in itself a finding about the gene and the disease.
ovarian carcinoma (4 papers, 2005 to 2024). A malignant neoplasm originating from the surface ovarian epithelium. "All showed that compared to levels in normal tissues, ST14 is overexpressed in ovarian cancer (P = 0.004)." (PMID 38468232, 2024). "In this study, we found that ST14 and TMEFF1 were overexpressed and interacted in ovarian cancer and both are independent risk factors for prognosis." (PMID 38468232, 2024). "To further explore the targets of ST14 in ovarian cancer, we analyzed the kinase, miRNA, and transcription factor target networks of the positively related gene set generated by GSEA." (PMID 38468232, 2024). "MTT, wound healing and Transwell assays results determined that knockdown of ST14 inhibited proliferation, migration and invasion of ovarian cancer cells in vitro, but the inhibitory effect was restored after adding TMEFF1 exogenous protein." (PMID 38468232, 2024). "We further validated this using ovarian cancer specimens and immunohistochemistry and found that ST14 is highly expressed in ovarian cancer, specifically in advanced stages and poorly differentiation groups, and is an independent risk factor for prognosis." (PMID 38468232, 2024). "A follow-up of patients with ovarian cancer (as of January 30, 2020) with univariate Kaplan–Meier analysis showed that the high expressions of ST14 and TMEFF1 were both correlated with shortened OS (P = 0.003; 0.001, respectively)." (PMID 38468232, 2024). "In this study, the results of Oncomine, UALCAN, and GEPIA database analysis showed that ST14 was significantly highly expressed in ovarian cancer and was related to the stage subgroup." (PMID 38468232, 2024). "Western blot results showed that knocking down ST14 in ovarian cancer CAOV3 and SKOV3 cell lines also decreased the expression of TMEFF1 (P < 0.05), indicating that ST14 regulates the expression of TMEFF1 in these cells." (PMID 38468232, 2024). "To further study the expression of ST14 based on different ovarian cancer research chips, we used the Oncomine database to identify six datasets containing ST14 expression data." (PMID 38468232, 2024). "Jin found that compared to that in the normal ovarian epithelium, ST14 is highly expressed in ovarian cancer." (PMID 38468232, 2024). "The GEPIA website was further used to analyze the expression of ST14 in 426 ovarian cancer specimens and 88 normal ovarian specimens, and results suggested that ST14 mRNA was significantly highly expressed in ovarian cancer (P < 0.05)." (PMID 38468232, 2024). "Multivariate Cox regression analysis found that ST14 expression and TMEFF1 expression were independent risk factors affecting the prognosis of patients with ovarian cancer (P = 0.026, 0.002)." (PMID 38468232, 2024). "Through immunofluorescence double staining, we found that the co-localization of TMEFF1 and ST14 in the cell membrane of different ovarian tissues and ovarian cancer cell line CAOV3." (PMID 38468232, 2024). "Tanimoto and Oberst found that compared with early ovarian cancer, ST14 expression is weaker in clinical specimens of advanced ovarian cancer, and ST14-positive patients showed a longer survival time." (PMID 38468232, 2024). "Among all 91 cases of ovarian cancer, 49 total cases showed high expression of ST14 and TMEFF1 at the same time, whereas 15 cases showed low expression at the same time." (PMID 38468232, 2024). "To better understand the role of ST14 in ovarian cancer, we analyzed the genes most relevant with ST14 and construct the PPI network using GeneMANIA and STRING database." (PMID 38468232, 2024). "We found that ST14 promotes migration and invasion of ovarian cancer cells by wound healing assay and Transwell assay in ovarian cancer." (PMID 38468232, 2024). "Based on the similar biological functions of TMEFF1 and ST14, we speculate that the interaction between them might affect their function in ovarian cancer." (PMID 38468232, 2024). "ST14 can promote the proliferation,invasion and metastasis of ovarian cancer by regulating TMEFF1." (PMID 38468232, 2024).
ovarian carcinoma (continued). "Therefore, the the expression and prognostic effect of ST14 in ovarian cancer is still controversial." (PMID 38468232, 2024). "We first discovered the interaction of TMEFF1 with ST14 in ovarian cancer." (PMID 38468232, 2024). "However, in the study on ovarian cancer, the expression of ST14 resulted in different conclusions." (PMID 38468232, 2024). "ST14 can regulate TMEFF1 expression to promote proliferation, migration and invasion of ovarian cancer cells." (PMID 38468232, 2024). "In order to further detect the role of ST14 and TMEFF1 interaction in ovarian cancer cells, MTT, Transwell and Wound healing assays were performed." (PMID 38468232, 2024). "The function of ST14-TMEFF1 in proliferation, invasion and metastasis of ovarian cancer will be detected by cytological experiments, which will provide a new research direction to explore the interaction between ST14 and TMEFF1 in ovarian cancer." (PMID 38468232, 2024). "In this study, we detected the expression of ST14 and TMEFF1 in 130 different ovarian cancer tissues through immunohistochemistry." (PMID 38468232, 2024). "Through immunoprecipitation, we found that ST14 and TMEFF1 interact in the ovarian cancer cells CAOV3, OVCAR3, and SKOV3." (PMID 38468232, 2024). "In this study, through immunohistochemistry, immunoprecipitation and double-labeled immunofluorescence assays we confirmed ST14 and TMEFF1 were expressed positively correlated, co-precipitated and co-localized in ovarian cancer." (PMID 38468232, 2024). "In summary, this shows that ST14 and TMEFF1 can effectively predict the prognosis of ovarian cancer patients." (PMID 38468232, 2024). "Overall, high expression of ST14 and TMEFF1 in ovarian cancer predicts higher tumor malignancy and a worse prognosis." (PMID 38468232, 2024). "Through analysis of the GEPIA website, it was also found that in ovarian cancer (TCGA tumor) and normal ovaries (GTEx), the expression levels of TMEFF1 and ST14 are positively correlated (R = 0.32, P = 1.1e-13)." (PMID 38468232, 2024). "We determined ST14 and TMEFF1 were highly expressed in ovarian cancer, indicating a higher degree of tumor malignancy and a worse prognosis." (PMID 38468232, 2024). "Cox regression model was used to analyze the relationship between the prognosis of ovarian cancer patients and different clinicopathological parameters, it was found that FIGO stage, ST14 expression, and TMEFF1 expression affected the survival time (P = 0.012, 0.005, 0.001, respectively)." (PMID 38468232, 2024). "We speculate that the relationship between ST14 and TMEFF1 in ovarian cancer could become a potential target for anti-cancer therapy." (PMID 38468232, 2024). "Thus, the specific mechanisms of interactions between ST14 and TMEFF1 affecting ovarian cancer still need to be studied in depth." (PMID 38468232, 2024). "ST14 and TMEFF1 co-localize and interact with each other in ovarian cancer." (PMID 38468232, 2024). "Therefore, in this study, we will explore the interaction between ST14 and TMEFF1 and their relationship with prognosis in ovarian cancer." (PMID 38468232, 2024). "Therefore, blocking the interaction site of ST14 and TMEFF1 protein may become a potential target for the treatment of ovarian cancer." (PMID 38468232, 2024).
breast tumors (3 papers, 2021 to 2024). "In addition, a higher ST14 expression level was identified in breast tumors as compared with that in normal tissues (Wilcoxon’s p value < 0.001) and in tumors with a lower methylation status (Wilcoxon’s p value < 0.001)." (PMID 34418985, 2021). "This revealed that both EPI (e.g. LLGL2, CLDN4, KRT7, ST14) and MES (e.g. SNAI1, VIM, AP1M1) genes positively correlated with PIEZO1 expression across all quintiles, whilst markers of luminal breast tumors (ESR1, FOXA1, PGR) negatively correlated in all instances." (PMID 38632473, 2024).
lung carcinoma (3 papers, 2013 to 2024). "From our previous identification of ZEB1-correlated genes in lung cancer using Affymetrix arrays, we had confirmed regulatory relationships for ST14, EpCAM, and ESRP1 upon ZEB1 gain- and loss-of-function." (PMID 24216980, 2013). "In the previous study, the downregulated genes CASP10 and CD177 and the upregulated genes BAK1, ST14, CD82, and MUC4 were detected as biomarkers for lung cancer by the joint sparse regression model." (PMID 35923697, 2022).
squamous cell carcinoma (3 papers, 2016 to 2023). A carcinoma arising from squamous epithelial cells. "For example, skin-specific overexpression of ST14/Prss14 under Keratin 5 promoter in mouse induced spontaneous skin hyperplasia advanced further into squamous cell carcinoma." (PMID 27167193, 2016). "Although SPINT1 is a serine protease inhibitor with several targets, including ST14 and HGFA, deregulation of the SPINT1/ST14 axis leads to spontaneous squamous cell carcinoma in mice and keratinocyte hyperproliferation in zebrafish preceded by skin inflammation in both models." (PMID 31519199, 2019).
thymoma (3 papers, 2019 to 2024). A neoplasm arising from the epithelial cells of the thymus. "TGFβ induced EMT in the thymoma cell line 427.1.86 was blocked when Prss14/ST14 message was knocked down." (PMID 31426843, 2019).
autosomal recessive congenital ichthyosis 11 (2 papers, 2017). "Genetic variants in the ST14 gene are responsible for autosomal recessive congenital ichthyosis 11 in humans." (PMID 28235824, 2017).
bladder cancer (2 papers, 2024 to 2025). "In addition, no apparent statistical correlation was also observed between the expression of HGF, MET, ST14, HPN, and HGFAC and the prognosis of patients with bladder cancer by GEPIA." (PMID 40299447, 2025).
colorectal cancer (2 papers, 2018 to 2024). A primary or metastatic malignant neoplasm that affects the colon or rectum. "ST14 overexpression significantly enhances the invasion ability of colorectal cancer cells and affects the adhesion of cells to the extracellular matrix (ECM)." (PMID 38468232, 2024). "ST14 is involved in the processes of cell adhesion and epithelial–mesenchymal transition (EMT), affects the adhesion of early colorectal cancer cells to the ECM and enhances invasion ability." (PMID 38468232, 2024). "However, whether dysregulated CDX2 levels correlate with ST14 and SPINT1 in clinical colorectal cancer specimen needs to be clarified." (PMID 30087389, 2018).
diffuse large B-cell lymphoma (2 papers, 2024 to 2025). "The ST14 expression level is high in Burkitt lymphoma (BL, median = 5.8) and diffuse large B-cell lymphoma (DLBC, median = 5.2) but very low in acute myeloid leukemia (LAML, median = 1.5), although all are at much lower levels in comparison to those of epithelial carcinomas." (PMID 39996720, 2025).
adenoma (1 paper, 2020). A neoplasm arising from the epithelium. "For module yellow, which is progressively up-regulated from normal stroma to adenoma to mCA, the top candidate hub genes consisted of CDH1, ST14, EHF, KRT8, and KIAA1217, all of which have important roles in epithelial cells, and/or are associated with tumour malignancy." (PMID 32218455, 2020).
cervical cancer (1 paper, 2018). A primary or metastatic malignant neoplasm involving the cervix. "Furthermore, the ST14 reporter constructs were validated in the non-intestinal cervical cancer HeLa cell line devoid of CDX238." (PMID 30087389, 2018).
colitis (1 paper, 2018). Inflammation of the colon. "The ST14 gene has been established as a critical tumor-suppressor gene in the gastrointestinal tract, as well as a suppressor of colitis and colitis-associated colon carcinogenesis in mice." (PMID 30087389, 2018).
colon adenocarcinoma (1 paper, 2024). "The ablation of ST14 in the epithelium of the small intestine of mice will lead to the rapid formation of colon adenocarcinoma." (PMID 38468232, 2024).
esophageal cancer (1 paper, 2019). A primary or metastatic malignant neoplasm involving the esophagus. "Prss14/ST14 is valuable as a marker for poor survival of the post-surgery esophageal cancer." (PMID 31426843, 2019).
esophageal squamous cell carcinoma (1 paper, 2019). Esophageal squamous cell carcinoma (ESCC) is a type of esophageal carcinoma (EC) that can affect any part of the esophagus, but is usually located in the upper or middle third. "Our careful examination on post surgery esophageal squamous cell carcinoma patients showed that the prognosis of disease free survival is extremely poor with Prss14/ST14 expression." (PMID 31426843, 2019).
inflammatory breast carcinoma (1 paper, 2024). An advanced, invasive breast adenocarcinoma characterized by the presence of distinct changes in the overlying skin. "Zoratti found that the serine protease ST14 specifically cleaves the inactive pro-form of the hepatocyte growth factor (pro-HGF), promotes the release of HGF, binds c-Met, and then promotes the proliferation and invasion of inflammatory breast cancer cells." (PMID 38468232, 2024).
insulinomas (1 paper, 2015). "A higher expression of MET (P = 0.0115), HGF (P = 0.0183) and ST14 (P = 0.0453) mRNA was observed in the three metastases in comparison to G1 insulinomas." (PMID 26435753, 2015).
metastatic cancer (1 paper, 2009). A carcinoma which has spread from the original site of growth to another anatomic site. "Another molecule in the IGF signaling pathway, ST14, a transmembrane serine protease, has been implicated in metastatic cancer, which utilizes a molecular program reminiscent of embryonic EMT." (PMID 19156209, 2009).
multiple sclerosis (1 paper, 2025). A progressive autoimmune disorder affecting the central nervous system resulting in demyelination. "Therefore, in multiple sclerosis brain ECs, MCAM plays a critical role by promoting the recruitment of pathogenic TH1 and TH17 lymphocytes, particularly ST14+ memory cells." (PMID 41388158, 2025). "ST14 was identified as an immune ligand for MCAM, which was enriched in CD4+ T lymphocytes that cross the BBB in multiple sclerosis lesions." (PMID 41388158, 2025).
muscular dystrophy (1 paper, 2024). Muscular dystrophy (MD) refers to a group of more than 30 genetic diseases characterized by progressive weakness and degeneration of the skeletal muscles that control movement. "Despite the weak effects, we observed in these data, we want to highlight St14, which occurred among the top10, and which was already mentioned in the context of muscular dystrophy in the 1980s." (PMID 39529156, 2024).
ovarian serous cystadenocarcinoma (1 paper, 2024). A malignant serous cystic epithelial neoplasm arising from the ovary. "ST14 gene mutations were present at a low incidence in ovarian serous cystadenocarcinoma." (PMID 38468232, 2024). "Among the 1680 ovarian serous cystadenocarcinoma patients, only 89 (5.3%) had mutations in the ST14 gene, and the type and frequency were as follows: amplification, 64 cases (3.8%); deep mutation, 17 cases (1.0%); missense mutation (unknown significance), eight cases (0.5%)." (PMID 38468232, 2024).
pancreatic adenocarcinoma (1 paper, 2017). "We also observed differential methylation of RMRM (reprimo), CLDN5, LHX1, NTPX2, SPARC and ST14, which are already reported as aberrantly methylated genes in pancreatic adenocarcinoma." (PMID 28423671, 2017).
pancreatic cancer (1 paper, 2019). "Similarly, loss of SPINT1 in human pancreatic cancer cells promotes ST14-dependent metastasis in nude mouse orthotopic xenograft models." (PMID 31519199, 2019).
SARS-CoV infection (1 paper, 2020). "Previous studies indicated that both TMPRSS4 and ST14 facilitate influenza A virus infection but neither had a role in SARS-CoV infection." (PMID 32404436, 2020).
serous cystadenocarcinoma (1 paper, 2024). A malignant serous cystic neoplasm usually involving the ovary or the pancreas. "Among subtypes, the expression of ST14 in serous cystadenocarcinoma is related to TNM stage and FIGO stage, and a later stage is linked to stronger expression." (PMID 38468232, 2024).
uremia (1 paper, 2023). A clinical syndrome associated with the retention of renal waste products or uremic toxins in the blood. "The upregulation of ST14 in PBMC may promote the inflammatory activation of endothelial cells in blood vessel, which is a common uremia-related complication." (PMID 36875100, 2023).
viral infections (1 paper, 2023). "NHBE and HSAEC cells express ST14 and TMPRSS11D, and both are mildly upregulated in the presence of the viral infections." (PMID 37821447, 2023).